ADAMTS20 (ADAM metallopeptidase with thrombospondin type 1 motif 20)
Description:
May play a role in tissue-remodeling process occurring in both normal and pathological conditions. May have a protease-independent function in the transport from the endoplasmic reticulum to the Golgi apparatus of secretory cargos, mediated by the GON domain.
Synonyms: ADAM-TS20; ADAMTS-20; GON-1
Tractability: Antibody: its Gene Ontology location is reachable by antibodies, with high confidence; UniProt places it where antibodies can reach, with medium confidence; UniProt predicts a signal peptide or a membrane-spanning region.
Gene: Protein-coding gene on chromosome 12 (43,352,771 to 43,552,203, reverse strand). Ensembl gene ENSG00000173157.
Subcellular location: Secreted, extracellular space, extracellular matrix
Subcellular location (Human Protein Atlas): Golgi apparatus; Primary cilium; Basal body; Cytosol; Microtubules; Mitotic spindle; Predicted to be secreted
Pathways (Reactome):
Disease: Defective B3GALTL causes PpS
Metabolism of proteins: O-glycosylation of TSR domain-containing proteins
Gene Ontology:
Molecular function: metalloendopeptidase activity; endopeptidase activity; metallopeptidase activity; zinc ion binding
Biological process: extracellular matrix organization; proteolysis; cilium assembly; pigment cell development; proteoglycan catabolic process
Cellular component: extracellular matrix; extracellular region
Genetic constraint (gnomAD): Loss-of-function variants: 182 observed, 217.37 expected, observed/expected ratio (o/e) 0.84, 90% interval 0.74 to 0.95. The upper end of that interval is the gene's LOEUF score, 0.95, which puts it in group 4 of 6, group 1 being the genes least tolerant of losing a copy. Missense variants: 2,193 observed, 2,169.6 expected, observed/expected ratio (o/e) 1.01, 90% interval 0.98 to 1.05. Synonymous variants: 738 observed, 727.78 expected, observed/expected ratio (o/e) 1.01, 90% interval 0.95 to 1.08.
Homologues: Orthologues: macaque ADAMTS20 (94% identical), chimpanzee ADAMTS20 (94% identical), pig ADAMTS20 (76% identical), dog ADAMTS20 (75% identical), mouse Adamts20 (71% identical), rat Adamts20 (70% identical), guinea pig ADAMTS20 (69% identical), rabbit ADAMTS20 (64% identical), tropical clawed frog adamts20 (56% identical). Paralogues in human: ADAMTS9 (50% identical), ADAMTS7 (22% identical), ADAMTS12 (21% identical), ADAMTS15 (20% identical), ADAMTS18 (19% identical), ADAMTS1 (19% identical), ADAMTS6 (19% identical), ADAMTS16 (19% identical), ADAMTS10 (19% identical), ADAMTS19 (18% identical), ADAMTS8 (18% identical), ADAMTS17 (18% identical), and 13 more.
Diseases named in the same sentence as ADAMTS20 in open-access papers:
ADAMTS20 is named in the same sentence as 40 diseases in open-access papers, as found by Europe PMC text mining. Sharing a sentence is not in itself a finding about the gene and the disease. The quoted sentences say what the papers report.
endometritis (4 papers, 2024 to 2025). An acute or chronic, usually bacterial infectious process affecting the endometrium. "Expression of ADAMTS20 has been reported to be upregulated in ewes with endometritis, and members of the ADAMTS family have been associated with divergent prolificacy of sheep and goats." (PMID 39080565, 2024). "Gene expression levels were considerably higher in endometritis-affected buffaloes than in resistant ones for the genes A2M, TLR2, IRAK3, CCl2, FCAMR, iNOS, ADAMTS20, KCNT2, MAP3K4, MAPK14, FKBP5, and EPHA4." (PMID 38459095, 2024).
colon cancer (2 papers, 2008 to 2015). "Given the fact that no ADAMTS-20 is being produced by cultured colon cancer cells, in contrast to colon cancer tissue, where the enzyme is being produced, as it was confirmed by both IHC and Western blot, it could be said that tumor micro-enviroment plays an important role in ADAMTS-20 expression." (PMID 25786261, 2015). "In proteolysis, we identified the subtilisin PCSK2, with 4-6 fold increases in 8 of its core probe-sets in MG-thymoma and increases in colon cancer, and the endopeptidases PHEX and ADAMTS20 (proteolysis), both up-regulated in MG-thymoma but not in colon cancer." (PMID 18545673, 2008).
glioma (2 papers, 2022 to 2023). A benign or malignant brain and spinal cord tumor that arises from glial cells (astrocytes, oligodendrocytes, ependymal cells). "Furthermore, the mutations of ADAM family members were assessed in gliomas, and ADAMTS20, ADAMTSL1 (ADAMTS-like protein 1), and ADAMTSL9 mutation probability was as high as 3%; other ADAM family members also had a series of mutations that were mainly concentrated in amplification." (PMID 36172139, 2022). "We subsequently found that ADAMTS20 and FREM3 were interrelated lower risk of glioma using Cox regression analysis, whereas LAMB4, MMP1, and MMP7 showed high risk of glioma." (PMID 37335645, 2023). "For the sake of clarifying the expression of BMGs in glioma, this study screened 9 BMGs that were upregulated in glioma (FBN2, FREM3, Lamb4, MEP1A, MMP1, MMP7, OPTC, EVA1A, and ADAMTS20) from TCGA -GTEX expression matrix." (PMID 37335645, 2023). "Among them, ADAMTS20 and ADAMDEC1 showed no expression in normal brain tissue, but their expression was significantly increased in glioma." (PMID 36172139, 2022). "The differences between the presence and absence of ADAMTS20 and ADAMDEC1 had obvious advantages in the prevention and identification of glioma in clinical treatment." (PMID 36172139, 2022).
breast invasive ductal carcinoma (1 paper, 2020). "The expression level of ADAMTS20 was also significantly associated with the histological grade of breast invasive ductal carcinoma." (PMID 33179733, 2020).
breast tumors (1 paper, 2008). "ADAMTS20 over-expression has not been carefully examined in melanoma, but has been observed in brain, colon and breast tumors." (PMID 18454205, 2008).
clear cell renal cell carcinoma (1 paper, 2021). "The analysis of the Human Protein Atlas database also showed that the expression of ADAMTS20 in clear cell renal cell carcinoma was significantly increased, which was consistent with the results of previous studies." (PMID 34603444, 2021).
cleft palate (1 paper, 2025). Cleft palate is a fissure type embryopathy that affects the soft and hard palate to varying degrees. "Mutations in the DLX6 and ADAMTS20 genes are associated with the development of cleft palate and other abnormalities in dogs." (PMID 40431567, 2025).
colorectal cancer (1 paper, 2022). A primary or metastatic malignant neoplasm that affects the colon or rectum. "As an anti-angiogenic member of the family, ADAMTS20 was found to be downregulated in colorectal cancer." (PMID 35402275, 2022). "ADAMTS20 was found to be downregulated in colorectal cancer and TTN was reported to be frequently detected in solid tumors including colorectal cancer." (PMID 35402275, 2022). "GPR155 I357S mutation in lung cancer and ADAMTS20 S1597P and TTN R7415H mutations in colorectal cancer were frequently detected at the time of acquired resistance." (PMID 35402275, 2022). "In addition, the GPR155 I357S mutation in lung cancer and ADAMTS20 S1597P and TTN R7415H mutations in colorectal cancer were frequently detected at the time of acquired resistance, indicating that these mutations have an important function in acquired resistance to chemotherapy." (PMID 35402275, 2022).
colorectal tumors (1 paper, 2015). "Using RT-PCR, the expression of ADAMTS-1, -4, -5 and ADAMTS-20 was estimated in colorectal tumors of different cancer stage and anatomic site and 3 cell lines of different aggressiveness." (PMID 25786261, 2015).
ectodermal dysplasias (1 paper, 2015). "Variants in and around ADAMTS20 may also act as modifiers of the phenotype in clefting syndromes that including syndactyly as part of the phenotypic spectrum, such as Van der Woude syndrome and the ectodermal dysplasias." (PMID 25798845, 2015).
embryonal carcinoma (1 paper, 2022). A non-seminomatous malignant germ cell tumor characterized by the presence of large germ cells with abundant cytoplasm resembling epithelial cells, geographic necrosis, high mitotic activity, and pseudoglandular and pseudopapillary structures formation. "Mutations in ADAMTS20, ARHGAP10, OR1L4, PDS5A, and RPLP0 were only found in mixed germ cell tumors, while mutations in B3GNT8, CAPN7, FAT4, GRK1, TACC2 and TRAM1L1 were only observed in embryonal carcinoma, and their mutation frequency was around 2%." (PMID 36713456, 2022).
glycosylation disorders (1 paper, 2024). "The second-best match (ADAMTS20) has weaker interactions, but still has, nevertheless, connections with proteins related to anticoagulative and glycosylation disorders." (PMID 38396603, 2024).
Hydrocephalus (1 paper, 2021). Hydrocephalus is an active distension of the ventricular system of the brain resulting from inadequate passage of CSF from its point of production within the cerebral ventricles to its point of absorption into the systemic circulation. "Adamts20-null mice show a white spotting defect and a high degree of hydrocephalus." (PMID 34058199, 2021). "In contrast, ADAMTS20 TSR2-8, with almost identical TSR domain structures compared with ADAMTS9, is completely dependent on B3GLCT for secretion, implying that the white spotting and hydrocephalus observed in B3glct knockout mice are due at least in part to loss of ADAMTS20 secretion." (PMID 34058199, 2021).
invasive breast carcinoma (1 paper, 2018). A carcinoma that infiltrates the breast parenchyma. "ADAMTS20 encodes a secreted metalloproteinase with increased protein expression in invasive breast carcinoma." (PMID 29566768, 2018).
melanoma (1 paper, 2008). A malignant, usually aggressive tumor composed of atypical, neoplastic melanocytes. "Given that cell survival is an integral component of melanoma progression, ADAMTS9 and ADAMTS20 are excellent candidates for participating in melanoma." (PMID 18454205, 2008). "Given the requirement of Adamts20 for Kit signaling and versican cleavage, it is intriguing to consider how dysregulation of signaling between ADAMTS20, Kit, and versican might contribute to melanoma progression." (PMID 18454205, 2008).
orofacial cleft (1 paper, 2015). A disorder of facial skeleton that is characterized by cleft lip and/or cleft palate that result in feeding, speech and hearing problems caused by failures during development. "This study presents independent genome-wide association studies that provide evidence of the involvement of ADAMTS20 in the development of orofacial clefts in dogs and humans." (PMID 25798845, 2015).
osteoporosis (1 paper, 2022). A condition of reduced bone mass, with decreased cortical thickness and a decrease in the number and size of the trabeculae of cancellous bone (but normal chemical composition), resulting in increased fracture incidence. "In conclusion, this report has described three rare missense variants in SELP, TGF-β2 and ADAMTS20 that alone or in combination could potentially be the underlying genetic determinant(s) contributing to early-onset familial osteoporosis and low BMD in the two-generation Maltese pedigree." (PMID 35205249, 2022). "In the present report, WGS of a two-generation Maltese pedigree with early-onset familial osteoporosis and low BMD identified three rare and evolutionary conserved missense variants within SELP (c.2177T>C), TGF-β2 (c.1136C>T) and ADAMTS20 (c.4090A>T)." (PMID 35205249, 2022).
Peters plus syndrome (1 paper, 2022). "Recently, it has been shown that inactivation of B3GLCT affects the secretion of ADAMTS20 in Peters plus syndrome (OMIM 261540)." (PMID 35205249, 2022).
cancer (3 papers, 2005 to 2022). A tumor composed of atypical neoplastic, often pleomorphic cells that invade other tissues. "ADAMTS-1 was mostly expressed by stroma cells, in contrast to ADAMTS-20 which was expressed by cancer cells." (PMID 25786261, 2015).
tumor (3 papers, 2015 to 2024). "Indeed, previous studies have shown that ADAMTS-20 is overexpressed in brain and breast carcinomas, suggesting that this protease could play a role in tumor progression." (PMID 25786261, 2015). "Amongst the upregulated matrisome‐associated genes in low HDM uLMS tumours, we found the ECM‐degrading MMP13 and ADAMTS20, further suggesting increased ECM proteolysis in uLMS tumours." (PMID 37078535, 2024). "In the present study, a signature for BRCA radiotherapy sensitivity prediction was developed based on the expression of six characteristic DEGs, including HOXB13, NKX2-2, ADAMTS20, LOC284930, ACTL8 and LOC101928978, in BRCA tumor samples compared with their paracancerous samples for the first time." (PMID 33179733, 2020).
infection (2 papers, 2021 to 2022). The state of being infected such as from the introduction of a foreign agent such as serum, vaccine, antigenic substance or organism. "ADAMTS20, NECTIN3 and WLS were selected to represent non-infection associated genes with higher expression in Holstein cells." (PMID 35061738, 2022).
peripheral neuropathy (1 paper, 2024). A disorder affecting the peripheral nervous system. "ADAMTS20 is included in both models but to our knowledge not previously reported in association with peripheral neuropathy." (PMID 38755266, 2024).
ADAMTS20 also shares sentences with these, for which no sentence is quoted: cleft lip (2 papers); blood disorders (1); ciliopathies (1); endometrial polyp (1); gastrointestinal disorders (1); hepatocellular carcinoma (1); Insulin resistance (1); lung carcinoma (1); mixed germ cell tumor (1); Obesity (1); osteoarthritis (1); Osteopenia (1); syndactyly (1); thrombotic thrombocytopenic purpura (1); thymoma (1); type 2 diabetes (1); van der Woude syndrome (1); Weill-Marchesani syndrome (1).